CTLA4 (cytotoxic T-lymphocyte associated protein 4)
Diseases named in the same sentence as CTLA4 in open-access papers (continued):
Sharing a sentence is not in itself a finding about the gene and the disease.
cancer (continued). "These trials will investigate the anti-cancer effect by simultaneously boosting both the innate immune activity, via anti-KIR, and the adaptive immune activity via anti-PD-1 or anti-CTLA4." (PMID 27756892, 2017). "Gene expression of PD-1 as well as CTLA-4, CD25, CD28, Foxp3, TGF-β and IL-10 was increased in most cancer patients compared to that in healthy adults." (PMID 28881603, 2017). "We observed a strong nuclear staining for Foxp3 in lymphocytes and cancer cells and strong membranous/cytoplasmatic reaction for CD4 and CD8, but low for CD25 and CTLA-4." (PMID 28831395, 2017). "Current clinical trials of checkpoint blockers, including anti-CTLA-4 and/or anti-PD1 have shown promising results in many different cancer types." (PMID 28947968, 2017). "Altogether, these results indicate that cancer cell-intrinsic activation of type-I IFN pathway is required for optimal in situ vaccination by radiation and anti-CTLA4, and is mediated via cGAS-STING." (PMID 28598415, 2017). "Subsequently, the examined studies were categorized into subgroups, including cancer types, CTLA-4 sources, and experimental methods, to minimize heterogeneity and to further investigate the prognostic role of CTLA-4." (PMID 28211499, 2017). "Taken together, this data indicates LAG3 acts as an immune-checkpoint receptor quenching the immune response, becoming a very attractive “druggable” receptor for cancer immunotherapy, especially in combination with PD1 and/or CTLA4 blockade." (PMID 28934318, 2017). "Our PSSMHCpan can not only help develop personalized antitumor vaccines, but also has great potential in other aspects of cancer immunotherapy, including designing dendritic cell vaccines, inducing DC-CTL, TCR-T, and assessing the PD-1/CTLA4 prognosis." (PMID 28327987, 2017). "Several strategies targeting Tregs in vivo have been employed with certain efficacy in cancer, including depletion with anti-CD25 antibodies and treatment with anti-GITR and anti-CTLA-4." (PMID 28265583, 2017). "The same search was operated on clinicaltrial.gov to identify ongoing clinical trials exploring PD-1/PD-L1 and CTLA-4 axis in EC, particularly focusing on POLE-ultra-muted and MSI-H cancer types." (PMID 29163851, 2017). "Along with an increase in the percentage of CD8+ T cells, cancer patients also had 170% higher levels of PD-L1+CD8+ T cells (p=0.0025) and 165% higher levels of CTLA-4+CD8+ T cells (p=0.0025)." (PMID 28936253, 2016). "Cancer patients had higher levels of BATF+CD4+ T cells, PD-L1+CD8+ T cells and CTLA-4+CD8+ T cells compared to healthy donors." (PMID 28936253, 2016). "Among major immune checkpoints, e.g. PD-1 and CTLA4, the pharmacologic blockage of CXCR4 and its endogenous ligand CXCL12 has appeared as a prime target for blocking strategies in the treatment of cancer patients." (PMID 27462860, 2016). "The FDA-approved Ipilimumab (anti-CTLA4), Nivolumab, and Pembrolizumab (anti-PD1) monoclonal antibodies are able to unleash the antitumor immune response in cancer patients, showing unprecedented responses in aggressive tumors." (PMID 27783034, 2016). "There still have a lot of clinical trials to evaluate the antibodies targeting the inhibitory receptors such as CTLA4, PD1, PDL1 and LAGs for the treatment of patients with different cancer." (PMID 27447564, 2016). "Immune checkpoint antibodies, such as anti-CTLA4 or anti-PD-1, can enhance the CTL response to solid tumors by “loosening the brakes” on the immune response to cancers, which originate from self-tissues." (PMID 26658107, 2015). "Although antibodies targeting the immune checkpoints CTLA-4 and PD1 proved efficient at inducing sustained clinical responses in cancer patients, harmful autoimmune side effects have been observed in a large number of patients." (PMID 26161423, 2015).
cancer (continued). "The great success of anti-cytotoxic lymphocyte antigen 4 (CTLA4) and anti-programed cell death protein 1 (PD1) in cancer treatment has encouraged more effort in harnessing the immune response through immunomodulatory molecules in various diseases." (PMID 26347744, 2015). "Targeting T-cell inhibitory check point molecules, including the T-cell inhibitory receptor cytotoxic T-lymphocyte antigen 4 (CTLA-4) and programed cell death 1 (PD1), is a relatively new therapeutic approach to cancer therapy." (PMID 25101247, 2014). "Previous studies in cancer patients and animals have suggested that ICOS+ T cells play an important role in the action of anti-CTLA-4, as well as having prognostic significance." (PMID 23626745, 2013). "Moreover, anti-CTLA-4 monoclonal antibody (mAb) therapy in preclinical cancer models produced antitumor activity, both as monotherapy and in combination with other therapeutic modalities, providing the rationale for clinical development of human monoclonal antibodies that target CTLA-4." (PMID 23873089, 2013). "However, we did not found any significant increased cancer risk in Caucasians, ethnicity may be an essential biological factor which influences CTLA-4 -1661A/G polymorphism through gene to gene interaction." (PMID 24376736, 2013). "Several strategies have been employed with certain efficacy in cancer, including depletion with anti-CD25 antibodies, treatment with anti-GITR and anti-CTLA-4." (PMID 21272332, 2011). "Further, across multiple cancer types, high ADM5 expression was associated with reduced patient survival in anti-PD1- and anti-CTLA4-treated patients but not in anti-PDL1-treated patients." (PMID 41776551, 2026). "Combined anti-PD-1/CTLA-4 blockade leads to a high rate of durable responses in dMMR/MSI-H non-CRC cancers comparing favourably to published trials using anti-PD-1/PD-L1 monotherapy." (PMID 41231502, 2026). "Not surprisingly, combined immunotherapy with anti-CTLA-4 and anti-PD-1, due to their synergism, gives better responses in cancer patients." (PMID 40109334, 2025). "Besides, according to our study, two crucial immune checkpoint genes, PDCD1 (PD-1) and CTLA-4, significantly correlate with TIL scores across most cancer types." (PMID 40108446, 2025). "Consequently, therapeutic approaches such as HPV vaccines and immune checkpoint inhibitors (e.g., anti-CTLA4, PD-L1, and PD-L2 antibodies) are becoming increasingly vital in treating HPV-related cancers." (PMID 40005446, 2025). "Importantly, the use of humanized CTLA4-knockin mice allowed us to interrogate the physiological consequences of targeting CTLA4 with a monoclonal antibody, ipilimumab, FDA-approved for various human cancers." (PMID 40100323, 2025). "Although anti-CTLA-4 treatment has yielded encouraging outcomes in clinical trials in some forms of cancer, recent studies have demonstrated that it offers no clinical benefit in the context of OSCC, even when combining CTLA-4 inhibitors with other ICIs." (PMID 40725864, 2025). "ICIs targeting cytotoxic T-lymphocyte-associated protein 4 (CTLA-4) and programmed cell death protein 1 (PD-1) or its ligand (PD-L1) inhibit negative immune regulation, thereby enhancing anti-cancer immune activity." (PMID 41295253, 2025). "Our pan-cancer analysis reveals its consistent upregulation in 33 malignancies, including GBM, where it strongly correlates with immunosuppressive molecules (PD-L1, CTLA-4, TGF-β, IL-10), suggesting a potential universal role in immune evasion." (PMID 41438981, 2025). "Immune checkpoint molecules, including CTLA4, PD1, and LAG3, serve crucial roles in immune homeostasis by modulating immune responses and preventing excessive tissue damage, which is often exploited by cancers and pathogens to escape immune control." (PMID 40459260, 2025). "Ultimately, CTLA-4 ICIs reprogram the TME, shifting it from a state of immune suppression to one of immune activation, allowing the body to mount a more effective attack on cancer cells." (PMID 39857692, 2025).
cancer (continued). "Based on the upregulation of other immune checkpoints after PD-1/PD-L1 blockade treatment, we focus on the combination with other ICBs, including CTLA-4, TIM-3, LAG-3, TIGIT, VISTA, and some emerging immune checkpoints, so as to provide evidence for improving the benefit of ICBs in cancers." (PMID 40861801, 2025). "CTLA-4 and PD-1 are negative checkpoint regulators of T cell immune function, and inhibition of these targets is being used as immunotherapies for various cancers." (PMID 39847577, 2025). "Notably, combining TLR agonists with immune checkpoint inhibitors such as PD-1/PD-L1, CTLA-4, TIGIT, and LAG3 has yielded synergistic effects and improved therapeutic outcomes across various cancer models." (PMID 41228373, 2025). "ICIs, such as anti–PD-L1 and anti–CTLA-4, have revolutionized cancer treatment, yet many patients do not derive benefit from these therapies, and novel immunotherapies often fail in clinical development." (PMID 40116579, 2025). "Also, several costimulatory molecules (e.g., CTLA4) play a crucial role in the pathogenesis of both SLE and cancer, suggesting a level of interconnectedness between these two conditions." (PMID 40225477, 2025). "T. Honjo and J. Allison made groundbreaking discoveries regarding the role of PD-1 and CTLA-4 inhibition in cancer therapy, which earned them the 2018 Nobel Prize in Physiology or Medicine." (PMID 40677703, 2025). "Anti-CTLA-4 antibodies have also been developed and characterized in vitro for canine cancer treatment; however, no clinical studies have been conducted to date to evaluate their clinical efficacy and safety." (PMID 40463388, 2025). "However, CTLA-4 affinity for these ligands is higher than CD28, therefore cancer cells tend to overexpress CTLA-4, consequently inhibiting T-cell-mediated immune responses." (PMID 39866237, 2025). "For the treatment of cancers, the US Food and Drug Administration (FDA) has approved PD-1 inhibitors (nivolumab, pembrolizumab, and cemiplimab), PDL-1 inhibitors (atezolizumab, durvalumab, and avelumab), and CTLA-4 inhibitors (ipilimumab)." (PMID 40149618, 2025). "Furthermore, a variety of cancer cells and antigen-presenting cells APCs demonstrate that IL-6, IFN-γ, TGF-β, CTLA-4 and programmed cell death protein 1 (PD-1) can all induce high levels of IDO1." (PMID 41035912, 2025). "The engineered antibodies targeting CTLA-4, Yervoy (ipilimumab), was approved by the FDA for the treatment of metastatic melanoma in 2011, which marked the first FDA approved ICI and started the rapid expansion of ICI for cancer immune therapy." (PMID 41294857, 2025). "Other anti‐cancer treatments associated with immune‐mediated cytopenias include immune checkpoint inhibitors that reactivate T‐cell mediated immunosurveillance against cancer cells, by targeting programmed death receptor 1 and its ligand (PD1 and PDL1) or CTLA‐4." (PMID 40517537, 2025). "The SWOG S1609 Dual Anti–CTLA–4 and Anti–PD–1 Blockade in Rare Tumors (DART) trial is a multicenter, prospective, open-label phase II study evaluating dual immune checkpoint inhibition with ipilimumab and nivolumab in rare cancers, including VSCC." (PMID 40723274, 2025). "As noted in the SIV-infection model, sodium butyrate supplementation did not provide immunological benefit in other murine cancer models, and its administration reduced the efficacy of anti-CTLA-4 therapy in these studies." (PMID 39903521, 2025). "Combining BCG and anti-CTLA-4 or anti-PD-1 therapies may enhance the immune activity within the NMIBC tumors and lead to a more efficacious immune response against the cancer." (PMID 40227644, 2025). "The treatment of cancer has brought about a paradigm shift with the introduction of immune checkpoint blockade (ICB) therapy, which is mostly dependent on inhibiting PD-1/PD-L1 and CTLA-4." (PMID 40276504, 2025).
cancer (continued). "PD-1 and CTLA-4 are co-inhibitory receptors expressed on the surface of T-lymphocytes, where they bind to their ligand (PDL-1 and CD80/CD86 ligands; respectively) expressed on the surface of regulatory immune cells and some types of cancers." (PMID 40108523, 2025). "In cancers, T cells are persistently stimulated by antigens, leading to the continuous high expression of LAG3 along with other co-inhibitory receptors such as PD-1, CTLA-4, and TIM-3." (PMID 40861801, 2025). "CRISPR‐Cas9 significantly enhances CAR‐T outcomes by enabling precise CAR gene integration, mitigating T‐cell exhaustion through knockout of inhibitory genes (e.g., PD‐1, CTLA‐4, and LAG‐3), and improving CAR‐T survival and anti‐cancer effects by interfering with programmed cell death." (PMID 40685330, 2025). "Blocking these interactions with monoclonal antibodies (Abs) targeting PD-1 (e.g., nivolumab, pembrolizumab), PD-L1 (e.g., atezolizumab, avelumab), CTLA-4 (e.g., ipilimumab), and more recently, Lymphocyte Activation Gene-3 (LAG-3) (e.g., relatlimab) has transformed cancer treatment." (PMID 40181971, 2025). "In contrast, validation of the identified prognostic trends for pathways in cohorts receiving modern anti‐cancer therapies (a‐PD‐1, a‐CTLA‐4 or their combination) did not yield uniform conclusions." (PMID 41017066, 2025). "While single-agent CTLA-4 or PD-1 blockade has significantly extended survival in some cancer patients, most do not respond." (PMID 39726592, 2024). "At the single‐cell level in non‐responders, nearly all immuno‐suppressive/exhausted markers as PD‐1, CTLA4, and BTLA, along with CCR6, a receptor comprising CCR6/CCL20 axis and promoting cancer progression, elevated consistently in peripheral HLA‐DR+CD8+ T cells." (PMID 39467150, 2024). "They found that a combination treatment with carbon ion irradiation and anti-CTLA4 mAb, but not anti-PD-L1 mAb, protected against cancer growth on both sides." (PMID 38474078, 2024). "Treg cells have the ability to limit the function of antigen-presenting cells by CTLA-4-dependent downregulation of CD80 and CD86, thereby playing a detrimental role in suppressing cancer progression by evading immune surveillance and suppressing the antitumor immune response." (PMID 38238581, 2024). "The idea of CTLA-4 target druggability is mainly based on the high-affinity binding of anti-CTLA-4 antibodies to CTLA-4 molecules, mediating Treg depletion or functional blockade, thereby enhancing T cell activation and the immune response to cancer." (PMID 38807592, 2024). "The expression of NNMT was closely related to the expression of many common immune checkpoints such as PD-L1 and CTLA-4, suggesting that NNMT may be involved in regulating the expression of immune checkpoint genes in cancer." (PMID 38809277, 2024). "According to Paul and Sa, curcumin inhibits expression of PD-L1 and reduces the expression of CTLA4 and the number of Treg cells, thereby providing anti-cancer effects, if not enhancing salutary immune activating/modulatory results." (PMID 38539487, 2024). "Furthermore, we assessed the correlations between GBP4 and immune checkpoint genes, including TIGIT, CTLA4, CD274 and PDCD1, across cancers." (PMID 38347243, 2024). "Extending our analysis to a pan-cancer cohort receiving immune therapy, patients with high LCP1 expression generally showed better survival outcomes with anti-PD1(P<0.001), anti-PD-L1(P<0.001) or anti-CTLA4 (P<0.001) immune therapy." (PMID 38977952, 2024). "Interestingly, our findings demonstrate that most epithelial cancer cells express PD-L1, whereas hybrid E/M and mesenchymal cancer cells reduce PD-L1 expression and upregulate CD80 and CD155 expression, which are the ligands of CTLA-4 and TIGIT receptors." (PMID 38914547, 2024). "Importantly, this regulatory mechanism establishes a basis for combination therapy with anti-CTLA-4 antibodies and NAT10 inhibitors in cancer." (PMID 38243170, 2024).
cancer (continued). "In addition, immune checkpoint therapies targeting Tregs, such as CTLA-4 blockade, anti-PD-1 therapy, OX40, and TIGIT, have also been reported to induce myocarditis, skeletal myositis, and colitis in cancer patients, while limiting the clinical application." (PMID 38644503, 2024). "Overall, CTLA4 and PDL1 play a role in the control of cancer cell metabolism." (PMID 38391918, 2024). "If agonist mAbs specific for PD1 or CTLA4 are also discovered, these may be combined with LAG3-specific agonist mAbs, either as separate molecules or as bispecifics, as is being done in cancer therapy." (PMID 38556085, 2024). "Despite the role of the different genetic variants in the CTLA-4 gene having not totally been elucidated, it is well established that polymorphisms in the CTLA-4 gene confer susceptibility to cancers." (PMID 39194710, 2024). "It has been reported that Tregs consume free fatty acids more effectively than Teffs in cancer patients due to the greater lipid uptake capacity, which is related to the specific expression of CD36, Foxp3, PD-1, TFEB, LKB1, CTLA-4, FOXO1, and co-stimulatory molecule OX40." (PMID 38644503, 2024). "Surprisingly, combination of both NDVs and dual blockade of PD-L1 and CTLA-4 did not have a synergistic effect in either of the cancer models we evaluated." (PMID 38328418, 2024). "In addition, anti-CTLA4 drugs have been studied in multiple preclinical studies and clinical trials, combined with anti-PDL1 or anti-OX40 antibodies for various cancers, including NSCLC, prostate cancer, mesothelioma, breast cancer, HCC, and pancreatic cancer." (PMID 38418707, 2024). "Allison’s team demonstrated that CTLA-4 acts as a “brake” on T cells and hypothesized that blocking CTLA-4 could unleash the immune system to attack cancer cells." (PMID 39584990, 2024). "Another in vitro study on melanoma cancer cells found that these cells could produce CTLA-4 and sCTLA-4, indicating a possible role of CTLA-4 and sCTLA-4 in cancer growth." (PMID 38243300, 2024). "Antibodies to the PD-1, PD-L1, and CTLA-4 proteins have demonstrated good efficacy in certain cancer types but unfortunately not in all cancers." (PMID 38954358, 2024). "Besides combination therapies with anti-CTLA-4, several clinical trials have investigated the combination of anti-PD-L1 with anti-VEGF therapies across different cancer types, showing promising results." (PMID 39034318, 2024). "By analyzing data from The Cancer Imaging Archive (TCIA), we discovered that CTLA4 might have better therapeutic effects on patients in the low BRS group." (PMID 39286249, 2024). "Humanized monoclonal antibodies have been developed, which target immune checkpoint receptors, including monoclonal antibodies blocking CTLA-4 (Ipilimumab), PD-1 (Pembrolizumab, Nivolumab) and PDL-1 (Atezolizumab, Avelumab and Durvalumab), allowing for immune-driven cancer killing." (PMID 39727645, 2024). "However, anti-PD-L1 antibody showed no enhancement of CTL activity in the presence of mesenchymal cancer cells, while the impaired CTL activity was largely restored by anti-CTLA-4 and anti-TIGIT antibodies." (PMID 38914547, 2024). "Honjo and Allison shared the Nobel Prize in Medicine in 2018 for their discovery that inhibition of PD-1 and CTLA-4 signaling can suppress negative immune regulation and provide a new form of cancer therapy." (PMID 38803496, 2024). "Other exosomal proteins have also been identified as important predictive biomarkers of GIC owing to create cancer-friendly condition to promote cancer metastasis, like exosomal Formin-like 2 (FMNL2), cytotoxic T lymphocyte antigen 4 (CTLA-4), RAB5A, aspartate β-hydroxylase, and so on." (PMID 38561768, 2024). "The expression pattern of B7-H4 distinguishes it from PD-1 and CTLA-4, with high mRNA expression and low protein expression in normal tissues, while demonstrating widespread expression in malignant tumors, particularly in OC." (PMID 39267740, 2024).